SNORA71B (small nucleolar RNA, H/ACA box 71B)
Synonyms: U71b; formerly RNU71B
Gene: Small nucleolar RNA gene on chromosome 20 (38,425,083 to 38,425,354, reverse strand). Ensembl gene ENSG00000235408.
Gene Ontology:
Biological process: RNA processing
Cellular component: nucleolus
Diseases named in the same sentence as SNORA71B in open-access papers:
SNORA71B is named in the same sentence as 2 diseases in open-access papers, as found by Europe PMC text mining. Sharing a sentence is not in itself a finding about the gene and the disease. The quoted sentences say what the papers report.
prostate carcinoma (2 papers, 2021 to 2022). A carcinoma that arises from epithelial cells of the prostate gland. "In addition, SNHG17 aggravates prostate cancer progression by positively regulating its homolog SNORA71B." (PMID 34782005, 2021). "Mechanistically, SNHG17 and its homolog SNORA71B were transactivated by signal transducer and activator of transcription 5A (STAT5A), and SNHG17 sponged with miR-339-5p and released the expression of STAT5A, thereby forming a regulatory loop and exacerbating prostate cancer progression." (PMID 35864871, 2022).
tumor (1 paper, 2022). "Previous literature describes that SNHG17 in prostate cancer increases the expression of its homolog snoRA71B through a positive feedback loop, which promotes tumor progression." (PMID 36185210, 2022). "A recent study demonstrated a positive feedback loop between SNHG17 and its homolog snoRA71B, promoting tumor progression." (PMID 36185210, 2022).